EGFR (epidermal growth factor receptor)
Diseases named in the same sentence as EGFR in open-access papers (continued):
Sharing a sentence is not in itself a finding about the gene and the disease.
prostate carcinoma (continued). "Cultured metastatic human prostate cancer cells C4-2B were labeled with 60 nm gold nanoparticles conjugated with C225 anti-EGFR antibodies (EGF receptor is over-expressed by these tumors) and DiI fluorescent dye to provide a label for viability and lineage tracing after transplantation." (PMID 21442036, 2011). "Curcumin also down-regulates EGFR signaling in prostate cancer cells by modulating levels of EGFR protein showing that curcumin inhibits the intrinsic EGFR tyrosine kinase activity and suppress ligand-induced activation of EGFR." (PMID 21858220, 2011). "As EGFR and p65 seem to be strong markers of recurrence in prostate cancer cells, further studies in larger cohorts would be of major interest to evaluate the clinical relevance of these two markers in prostate cancer tissues." (PMID 20216540, 2010). "The progression of prostate cancer is accompanied by the overexpression of EGFR (epidermal growth factor receptor) in a very large majority of cases, suggesting that this may play a mechanistic role." (PMID 27713352, 2010). "We therefore concluded that the supra-additive anti-tumor effects observed with the sunitinib-docetaxel combination might support innovative strategies in the management of advanced prostate cancer, using simultaneous treatments targeting EGFR." (PMID 27713352, 2010). "In support of this possibility, a recent study using a dual EGFR/HER2 kinase inhibitor in prostate cancer cell lines showed that an HER2/ERBB3 signalling pathway protected the AR from degradation at low androgen concentrations through an AKT-independent pathway." (PMID 17211467, 2007). "This suggested that autocrine EGFR signalling present in prostate carcinomas may contribute to E-cadherin repression in these tumours." (PMID 17406365, 2007). "As prostate cancer metastasises to the liver in over half of all patients with metastatic disease, we sought to explore the correlative expression levels of EGFR and E-cadherin in the presence of parenchymal cells of the liver." (PMID 17406365, 2007). "As we have previously shown that prostate carcinoma cells present autocrine EGFR signalling, we determined whether this also invoked STAT3 activation." (PMID 16804520, 2006). "Epidermal growth factor receptor signalling, upregulated in an autocrine manner in prostate carcinomas, was shown to be responsible, at least in part, for the downregulation of cadherin-mediated adhesion and levels of molecules noted in these tumours as it is in many other carcinomas." (PMID 15655536, 2005). "Furthermore, this work suggests that in human prostate cancer cells ligand-specific differential intracellular trafficking of the EGFR plays a major role in regulating its expression." (PMID 10360641, 1999). "Additionally, lycopene could alleviate the prostate cancer risk by modulating the growth genes like cyclin-dependent protein kinase 7 (CDK7), B-cell lymphoma 2 (BCL2), epidermal growth factor receptor (EGFR), and insulin-like growth factor 1 (IGF-1) receptor." (PMID 40013157, 2025). "It has been suggested that nearly 20% of all prostate cancers may have activated EGFR signaling." (PMID 36869937, 2023). "Additionally, although EGFR inhibitors false in prostate cancer, epiregulin could be a therapeutic target for patients with castration-resistant prostate cancer." (PMID 36994208, 2023). "In addition, TAMs was reported to regulate murine breast cancer stem cells through a novel paracrine EGFR/Stat3/Sox-2 signalling pathway and promote prostate cancer stem cells self-renewal and prostate cancer metastasis via activating β-catenin/STAT3 signalling." (PMID 38041196, 2023). "Also, for exploring the epidermal growth factor receptor (EGFR) in hormone-resistant prostate cancer, PC-3 cells with no susceptibility to androgen are a perfect model." (PMID 36926328, 2023).
prostate carcinoma (continued). "For example, nuclear translocation of epidermal growth factor receptor (EGFR) or androgen receptor (AR) associated with EVs released from prostate cancer cells and taken up by indolent receptor cells (i.e., cells without EGFR/AR) activated distinct signaling pathways in the latter." (PMID 36010551, 2022). "Thus, it may be possible that UCH-L1 mediated deubiquitination and stabilization of EGFR activates the PI3 K/Akt signaling in prostate cancer cells." (PMID 34745437, 2021). "Besides, MOLBCH could regulate the male reproductive function by affecting “Prostate cancer”, “Endocrine resistance”, “Relaxin signaling pathway”, “EGFR tyrosine kinase inhibitor resistance” and “Prolactin signaling pathway”." (PMID 33500463, 2021). "Strong expression of YB-1 and EGFR are closely related to the Gleason score, histological grade, and bone metastasis, suggesting that YB-1 and EGFR may be important factors that promote the progression of prostate cancer." (PMID 34696665, 2021). "Therefore, we speculate that WFDC2 inhibits prostate cancer metastasis by inactivating EGFR signaling." (PMID 32678075, 2020). "Therefore, the combination of EGFR inhibitor and LXRs agonist may become a potential treatment strategy for prostate cancer, especially metastatic prostate cancer." (PMID 33224867, 2020). "Previous reports suggested that miR-146-5p represses EGFR expression through binding to its 3'-untranslated region, and that the reconstitution of miR-146b-5p may be useful for the treatment of invasive prostate cancer." (PMID 31756185, 2019). "Furthermore, AR has been shown to regulate EGFR expression in prostate cancer cells." (PMID 31151317, 2019). "Interestingly, when characterising CTCs according to the presence of AR, we found that 100% of patients with AR-positive CTCs were EGFR-negative in the prostate cancer tissue, whereas up to 75% of patients with AR-negative CTCs presented EGFR-positive tissue (p= 0.5)." (PMID 29050295, 2017). "Thus, loss of miR-133 and miR-146a may be attributed to enhancement of EGFR signaling, leading to aggressive prostate cancer progression." (PMID 28445135, 2017). "As an oncogene, full length EGFR has been identified in exosomes isolated from prostate cancer cells and prostate cancer patient serum, which suggested that presence of exosomal EGFR in prostate cancer patient exosomes may present a novel approach for measuring of the disease state." (PMID 27756426, 2016). "Furthermore, EGFR was inhibited in berberine treatment of prostate cancer cell lines." (PMID 27738318, 2016). "Interestingly, our data suggests that miR-3622b directly represses EGFR in prostate cancer." (PMID 27611943, 2016). "Moreover, we selected three primary prostate cancer cell lines, LNCaP, PC3 and DU145, which are widely used and representative of advanced and highly tumorigenic prostate cancer to characterize the correlation between EGFR and ZNF216 expression through a Real-Time quantitative RT-PCR analysis." (PMID 27732953, 2016). "Besides the conventional EGFR inhibitors erlotinib and gefitinib, the herbal flavonoid luteolin showed effect in suppressing EGFR by down-regulating the Ser/Thr kinase activity of cyclin G-associated kinase (GAK) in prostate cancer cells." (PMID 26305257, 2015). "Hence, it is rational to speculate that MAPK/ERK pathway via EGFR stimulation may contribute to modulation of ABCD3 gene expression in prostate cancer." (PMID 25802834, 2015). "With the MMP16 and EGFR, men with the genotype combination of GA/AA and AA in a SNP pair of rs1401862 and rs6964705 tended to be less likely (OR = 0.58, p-value = 0.011) have aggressive prostate cancer than other genotype combinations of the SNP pairs in the CGEMS group." (PMID 23593148, 2013). "EGFR expression may have a role in the development of prostate cancer." (PMID 22546016, 2012).
prostate carcinoma (continued). "Interestingly, we have recently reported that luteolin also blocks EGFR gene transcription and a number of genes in the EGFR signaling pathway in PC-3 human prostate cancer cells demonstrating that this bioflavonoid apparently targets growth regulatory pathways." (PMID 21731475, 2011). "The potential utility of anti-EGFR treatments could be analyzed in EGFR-expressing prostate cancer." (PMID 27713352, 2010). "Collectively, our results identify a novel, ETV1‐dependent, oncogenic pathway in prostate cells and highlight the potential therapeutic outcome of coinhibition of EGFR and STAT3 in prostate carcinomas with ETV1 overexpression." (PMID 40808640, 2025). "This imaging method provided insights into thedistinct behaviors of mono- vs bis-substituted peptide conjugatesin live PC-3 prostate cancer cells, known to overexpress GRPR, andin A431 cells, known to overexpress the epidermal growth factor receptor(EGFR)." (PMID 41425801, 2025). "In prostate cancer, FBXW2 reduced epidermal growth factor receptor (EGFR) protein stability, thus suppressing cell proliferation and metastatic ability." (PMID 40721413, 2025). "Obviously, the main signaling pathways engaged in the targets of FSH for tumor treatment were Pathways in cancer, Prostate cancer, PI3K-Akt signaling pathway, EGFR tyrosine kinase inhibitor resistance, and Proteoglycans in cancer." (PMID 40230723, 2025). "The combination of quercetin-resveratrol can reduce the levels of EGFR, EGR3 and IL6, and increase the levels of IGFBP7 and NKX3.1, which can play an anti-prostate cancer role." (PMID 40490812, 2025). "It has been reported that MCM7 regulates the splicing of EGFR and PDGFR in human prostate cancer cells." (PMID 40789837, 2025). "Conversely, in prostate cancer and related cell lines, TNS4 is downregulated and exhibits a context-specific function by downregulating EGFR expression, indicating a different role in this context." (PMID 40906372, 2025). "We previously reported that treatment with caffeic acid phenethyl ester (CAPE) suppressed the cell proliferation, tumor growth, as well as migration and invasion of prostate cancer (PCa) cells via inhibition of signaling pathways of AKT, c-Myc, Wnt and EGFR." (PMID 39819475, 2025). "The main pathways are closely related to the pathways in cancer, prostate cancer, PI3K-Akt signaling pathway, EGFR tyrosine kinase inhibitor resistance, endocrine resistance, etc." (PMID 40826712, 2025). "In prostate cancer, FBXW2 facilitates epidermal growth factor receptor ubiquitination and degradation, thereby inhibiting EGF-induced growth and metastasis." (PMID 40225854, 2025). "To confirm the cell-type specificity of BsAb-mediated targeting, we analyzed mRNA-LNP delivery to EGFR+ve (EGFR-positive), PSMA+ve (PSMA-positive) LNCaP prostate cancer cells." (PMID 40235853, 2025). "In prostate cancer cells, STAP-2 interacts with and stabilizes epidermal growth factor receptor (EGFR) after stimulation, resulting in the upregulation of EGFR signaling, which contributes to cancer-cell proliferation and tumor progression." (PMID 38745775, 2024). "In accordance with observations made in breast and prostate cancer cells, we found that CXCR7-mediated EGFR activation also appears to be ligand-independent in primary human macrophages." (PMID 38472446, 2024). "By inhibiting TGFα-EGFR signaling, miR-152 also downregulated downstream genes MMP2 and MMP9, further suppressing the invasive and migratory potential of prostate cancer cells in vitro." (PMID 39606232, 2024). "EGFR, located in membrane rafts, mediates the PI3K/AKT signaling pathway, thereby promoting the survival of prostate cancer tissues." (PMID 39771106, 2024).
prostate carcinoma (continued). "STAP-2 upregulates EGFR-mediated signaling, enhancing STAT3 activity in DU145 prostate cancer cells." (PMID 38745775, 2024). "The enriched KEGG terms of the downregulated DEGs included prostate cancer (KEGG:05215), EGFR tyrosine kinase inhibitor resistance (KEGG:01521), and the MAPK signaling pathway (KEGG:04010)." (PMID 39451253, 2024). "A study reported that miR-N5 targets the 3’-UTR of CREBBP to suppress its expression, which in turn mediates H3K56 acetylation in the promoter regions of EGFR, β-catenin, and CDH1 in prostate cancer." (PMID 38493218, 2024). "In prostate cancer cells, the pro-inflammatory chemokine receptor CXCR7 interacts with EGFR, and its overexpression leads to an increased phosphorylation of EGFR." (PMID 39769452, 2024). "A different research found that the long noncoding RNAs EGFR and LOXL1-AS1were expressed at a low level, but the doxorubicin-resistant prostate cancer DU-145 cells exhibited an overexpression of the microRNA miR-let-7a-5p." (PMID 39512820, 2024). "In contrast, FAM66C is elevated in prostate cancer, and high FAM66C expression promotes tumour growth by activating EGFR-ERK signalling through inhibition of the proteasome pathway." (PMID 37980632, 2023). "In studies carried out on prostate cancer cells, curcumin has been reported to interact with the mitogen-activated protein kinase (MAPK), epidermal growth factor receptor (EGFR), and NF-κB signalling pathways." (PMID 37176840, 2023). "Enrichment analysis by KEGG, revealed that PDL1-related proteins are mainly involved in the regulation of epidermal growth factor receptor (EGFR) tyrosine kinase inhibitor resistance, insulin resistance, the Erbb signaling pathway and prostate cancer." (PMID 36760573, 2023). "It is already established that the epidermal growth factor receptor (EGFR) participates in tumorigenesis and progression of prostate cancer." (PMID 37576552, 2023). "In fact, EGFR transactivation induced by PGE2 has been observed in many tumor types, such as endometrial adenocarcinomas, gastric cancer, and prostate cancer." (PMID 37190301, 2023). "For example, excessive ROS can inhibit Epidermal Growth Factor Receptor (EGFR)-mediated Phosphatidylinositol 3-kinase (PI3K)/Akt signaling pathway and block the proliferation of androgen-independent prostate cancer cells." (PMID 37790761, 2023). "In particular, EGFR, MAPK3, and MAPK1 are involved in the HIF-1, estrogen, FoxO, and Rap1 signaling pathways as well as in central carbon metabolism in cancer, prostate cancer, focal adhesion, and gap junction pathways." (PMID 36430946, 2022). "As Ki67, HER1, and HER2, members of the epidermal growth factor receptor (HER) family are also up regulated in prostate cancer." (PMID 35681707, 2022). "In prostate cancer, SPINK1 is also mediated by EGFR and is incidentally related to aggressive disease in patients, so it has been used as a plausible target therapy in prostate cancer." (PMID 36053457, 2022). "Receptors of the EGFR/ERBB family are tightly correlated with poor prognosis, drug resistance, cancer metastasis, and lower survival rate of prostate cancer patients." (PMID 35954439, 2022). "We previously demonstrated that STAP-2 binds to epidermal growth factor receptor (EGFR) and facilitates its stability and activation of EGFR signaling in prostate cancer cells." (PMID 36410436, 2022). "NDRG1 overexpression has also been shown to inhibit the downstream targets of EGFR signaling, e.g., MEK1/2 or ERK1/2, in pancreatic and prostate carcinoma cells." (PMID 36160437, 2022). "Cell Senescence caused the differential expression of six genes belonging to the KEGG Pathway Prostate Cancer (PDGFRB, PDGFRA, CCNE2, E2F2, EGFR and ZEB1)." (PMID 35205253, 2022). "In contrast, molecular pathways that inhibit prostate cancer metastasis include the role of WFDC2 (WAP four-disulfide core domain 2), which downregulates SNAI/snail expression and inhibits EGFR (epidermal growth factor receptor)." (PMID 35317831, 2022).
prostate carcinoma (continued). "In the pathway networks of PBDE-treated HepG2 cells, EGFR appeared at the crossroad of HIF-1 and estrogen signaling for BDE-47 and was shared by prostate cancer and adherens junction pathways for BDE-209." (PMID 36430946, 2022). "MiR-137 also inhibits prostate cancer cell migration and epithelial-mesenchymal transition (EMT) by negatively regulating the epidermal growth factor receptor/extracellular signal-regulated kinase (EGFR/ERK) through LGR4 targeting." (PMID 33946652, 2021). "The top 30 protein targets with high frequency were CCND1, EGFR, ESR1, and MYC, which can be used as the potential targets of XHP in the treatment of prostate cancer." (PMID 35342388, 2021). "The relationships between EGFR tyrosine kinase inhibitor resistance, Relaxin signaling pathway, AGE-RAGE signaling pathway, and prostate cancer have been widely investigated and reported in the previous works." (PMID 34131148, 2021). "All the important changes lead to the regulation of EGFR‐MAPK‐ERK signaling and ultimately affect the role of EWI‐2 in the regulation or inhibition of prostate cancer metastasis." (PMID 33605506, 2021). "Specifically, half of the “prostate cancer” pathway DEGsSD had previously been referred to in the literature (AR, CDKN1A, CTNNB1, EGFR, KLK2, NKX3-1, PDGFRA, SRD5A2)." (PMID 34768937, 2021). "Evidence from prostate cancer similarly indicated that both EGFR and HER2 regulate metastasis to bone, the most prominent site of prostate cancer metastasis." (PMID 34206026, 2021). "Subsequently, Pim1 increased the RTK protein expression, including EGFR, HER2, and HER3 through Cap-independent translation, resulting in the resistance of prostate cancer cells to AKT inhibition." (PMID 34267653, 2021). "To date, study has suggested that the inhibition of autocrine EGFR signaling increases E-cadherin expression and promotes EMT in human prostate carcinoma upon co-culture with hepatocytes." (PMID 34147083, 2021). "In human LNCaP prostate cancer cells, radiation-induced PARP activation is enhanced through EGFR-ERK signalling." (PMID 32093123, 2020). "DHT increases both epidermal growth factor receptor (EGFR) numbers and receptor–ligand affinity in androgen-sensitive prostate cancer cells; this correlates with increased EGF binding and an enhanced mitogenic response to EGF." (PMID 32326308, 2020). "In vitro studies have shown that inhibition of cell viability of prostate cancer cells by GT3 is the result of a multipronged effect that involves the activation of the JNK pathway and suppression of NF-κB via downregulation of EGFR and Id-1." (PMID 32414345, 2020). "Curcumin interferes with a number of cellular pathways (in vivo and in vitro) in prostate cancer, including mitogen-activated protein kinase (MAPK), epidermal growth factor receptor (EGFR), and nuclear factor κ (NFκB)." (PMID 33202681, 2020). "For example, AR, EGFR, DDR2 and MAP2K2 were connected with mtDNA genes in prostate cancer, and TMPRSS2, NF1, PIK3CA, BRCA1 and TOP1 were the top neighbors of mtDNA genes in multiple cancer types." (PMID 32024997, 2020). "This receptor activates EGFR, which is directly responsible for the activation of the Src → FAK pathway and cancer cell migration, as shown on prostate cancer cells." (PMID 32466280, 2020). "Consistently, EGFR inhibitor Afatinib decreased p-EGFR and p-AKT on PC3 and DU145 prostate cancer cell lines, in a dose-dependent manner." (PMID 33224867, 2020). "Using immunomagnetic selection via EpCAM, HER2, and EGFR, a patient was defined as CTC+ if overexpression of one of the four prostate cancer related genes was detected." (PMID 33014830, 2020). "In prostate cancer, it has been shown that P2Y2R cooperates with EGFR to promote cell invasion and metastasis through the ERK1/2 pathway, suggesting a therapeutic possibility using purinergic blockers to treat this type of cancer." (PMID 31249523, 2019).